EGFR (epidermal growth factor receptor)
Diseases named in the same sentence as EGFR in open-access papers (continued):
Sharing a sentence is not in itself a finding about the gene and the disease.
lung cancer (continued). "Lung cancer is the most frequent cause of cancer-related deaths worldwide, and mutations in the kinase domain of the epidermal growth factor receptor (EGFR) are a common cause of non-small-cell lung cancers, which is a major subtype of lung cancers." (PMID 32085409, 2020). "In basic research, EGFR mutant lung cancer cell lines were reported to have better radiosensitivity in low dose fractionation." (PMID 32693792, 2020). "In another study, overexpression of miR‐134 suppressed the proliferation of lung cancer cells by down‐regulating the expression of EGFR." (PMID 32916774, 2020). "EGFR-targeted regimens (tyrosine kinase inhibitors and antibodies) have been proved as effective therapeutic options against lung cancer and colorectal cancer, while also displaying prospective applications in gastric cancer." (PMID 31912229, 2020). "Currently, the choice of first‐line treatment for advanced non‐small cell lung cancer (NSCLC) depends on the presence of genetic aberrations, such as mutations of epidermal growth factor receptor (EGFR) and translocations of anaplastic lymphoma kinase (ALK)." (PMID 31808285, 2020). "Tissue sections from lung cancer and control groups were treated with EGFR, HER2, and HER3 antibodies, and PLA was carried out." (PMID 32922539, 2020). "Treatment of lung cancer cell lines resistant to the EGFR monoclonal antibody cetuximab with the c-Src inhibitor dasatinib, led to a loss of nuclear EGFR and a re-sensitization to cetuximab treatment." (PMID 32517369, 2020). "The first studies with plasma-derived EVs focused on the analysis of EGFR in lung cancer and glioblastoma and KRAS in pancreatic cancer." (PMID 33575258, 2020). "This complex inhibits the proliferation and promotes the differentiation of lung tumor cells via inhibiting activating protein-2 (AP-2), which result in re-sensitization of EGFR-TKIs resistant lung cancer cells." (PMID 32293355, 2020). "What are the effectiveness and safety of osimertinib mesylate in the management of intracranial metastatic disease from non–small cell lung cancer with alterations in the epidermal growth factor receptor?" (PMID 32211870, 2020). "BRACHYURY confers survival advantage to the lung cancer cells in response to treatment with various doses of the epidermal growth factor receptor (EGFR) inhibitor." (PMID 32695672, 2020). "Vitamin D receptor (VDR), a critical player in vitamin D signaling axis, is highly expressed in EGFR-mutant lung cancer cells, making them intrinsically sensitive to 1,25(OH)2D3." (PMID 32292420, 2020). "A recent study of young patients with nonsmall cell lung cancer showed that higher frequency of ALK and HER2 genetic alterations were associated with young age, while, mutations in KRAS, STK11, and EGFR exon 20 are more common in older patients." (PMID 32657049, 2020). "We and others have previously reported that NF-κB was activated in acquired resistance to EGFR TKIs in in vitro and in vivo models and patient samples of EGFR-mutant lung cancer." (PMID 33014814, 2020). "Multiple studies in mouse models of EGFR mutant lung cancer have shown the utility of combination therapies in overcoming treatment resistance." (PMID 32117764, 2020). "Afatinib decreases phosphorylation between ErbB dimers more effectively than erlotinib and it has been reported to overcome therapy resistance to EGFR TKI in lung cancer clinically." (PMID 32143669, 2020). "The lung cancer line HCC827 has a typical EGFR tyrosine kinase domain deletion (E746-A750) that is associated with a reduced survival, frequent lymph node metastasis, and poor chemosensitivity." (PMID 33260400, 2020). "Lung adenocarcinoma (LADC) is the most common subtype of lung cancer worldwide and the epidermal growth factor receptor (EGFR) has a great influence on its clinical course, mainly due to the influence of different phenotypes." (PMID 33050100, 2020).
lung cancer (continued). "Exon 19 deletion within EGFR β3‐αC loop affecting kinase activity and driving lung cancer has been described." (PMID 32757330, 2020). "The study using the inducible EGFR T790M-L858R transgenic mouse models suggested that C/EBP beta is dispensable for lung tumorigenesis in EGFR-driven murine lung cancer." (PMID 32983988, 2020). "A completely different and poorly understood mechanism abolishing sensitivity towards EGFR TKI involves the histological transformation into small cell or sarcomatoid lung cancer phenotypes." (PMID 32397977, 2020). "This study revealed 85 unique EGFR e20ins and the most frequent insertions in 547 lung cancer patients, which is helpful for prioritizing drug designing and clinical trials for common insertions." (PMID 32412152, 2020). "In 203 lung cancer tissue samples, we detected a total of 313 EGFR GAs: 253 Substitution/Indels (including 250 Substitutions/Shortindels and 3 LongIndels, with 5 SNVs were belonging to germline mutation), 58 gene amplifications, and 2 fusions." (PMID 33219256, 2020). "We first examined the human lung cancer cell lines (HCC827 and H1975) to determine the distribution of mutated EGFR sequences in EVs." (PMID 32722209, 2020). "In this study, we evaluated the Sel-Cap lung cancer panel, an NGS-based genotyping platform for the detection of EGFR mutations in patients with NSCLC, and we focused specifically on its diagnostic performance while serving as a liquid biopsy platform." (PMID 33266057, 2020). "EGFR is one of the critical therapeutic targets in NSCLC lung cancer, and the A549 cell line is sensitive to different types of EGFR inhibitors." (PMID 32774169, 2020). "In lung cancer, a cancer-related SNP, telomerase reverse transcriptase (TERT) rs2736100, was shown to be associated with susceptibility to EGFR mutations in NSCLC." (PMID 33126605, 2020). "OSI has been approved as a first-line treatment of EGFR-mutant lung cancer and for metastatic EGFR T790M-mutant non-small cell lung cancer." (PMID 33008019, 2020). "miR-146a expression is significantly lower in the lung cancer tissue compared with the “normal” tissue from control subjects and is considered to act as a tumor suppressor by targeting epidermal growth factor receptor (EGFR) expression." (PMID 33294082, 2020). "Despite the development of third-generation EGFR-TKIs targeting T790M mutant lung cancer, resistance to EGFR-TKIs remains to be one of the most important issues affecting survival of patients." (PMID 32552717, 2020). "Curcumin has this promising capability to increase the effectiveness of radiotherapy in the treatment of lung cancer by targeting different signalling pathways such as epidermal growth factor receptor and NF κB." (PMID 32838749, 2020). "Delivery of vitamin D based drug payloads with CYP24A1 inhibitors via a tumor-targeted system was effective without causing side-effects and appears to be promising as a new therapy for EGFR TKI resistant lung cancer." (PMID 32180081, 2020). "More specifically, predictive models for EGFR and KRAS mutation status in lung cancer were developed." (PMID 32107398, 2020). "We then examined lung cancer tumor data from The Cancer Genome Alta (TCGA), which also revealed an elevated TF level in EGFR-mut tumors." (PMID 32923403, 2020). "As most patients with epidermal growth factor receptor (EGFR)‐mutant non‐small cell lung cancer (NSCLC) develop progressive disease after treatment with osimertinib, it is important to develop more effective treatment options." (PMID 32495514, 2020). "By using our models of acquired EGFR TKI resistance we were able to study the acquisition of resistance to EGFR TKIs in lung cancer cells and develop a combination therapy with the potential to overcome EGFR TKI resistance." (PMID 32123859, 2020). "Epidermal growth factor receptor (EGFR) gene mutations predict tumor response to EGFR tyrosine kinase inhibitors (EGFR‐TKIs) in non‐small cell lung cancer (NSCLC)." (PMID 31691525, 2020).
lung cancer (continued). "SCLC transformation from NSCLC has rarely been observed in EGFR-wild type lung cancers or during ALK-targeted therapy and programed cell death-1 (PD-1/L)-directed immunotherapy." (PMID 35582610, 2020). "Our results showed that the regulation of miR‐34a‐5p‐ and HOTAIR‐mediated inhibition of EMT and subsequently growth and metastasis by the combination of BBR and EGFR‐TKI gefitinib in lung cancer cells." (PMID 32248643, 2020). "First, the acquired resistance mechanism induced by the OPN/integrin αVβ3 pathway was confirmed only in EGFR-TKI-resistant PC9 cells, and our findings should be validated in various EGFR-TKI-resistant lung cancers." (PMID 33287873, 2020). "We found that the five-year mortality rates were lower in patients with PAK1-negative than in PAK1-positive EGFR mutant lung cancer." (PMID 33261184, 2020). "Targeted agents that display activity in treating other lung cancer sub-types (e.g., EGFR- and ALK-inhibitors in NSCLC) are relatively ineffective for SCLC because these pathways are generally not dysregulated in SCLC." (PMID 32224870, 2020). "Metformin inhibited proliferation and promoted apoptosis of lung cancer cells, especially those with acquired EGFR TKI resistance." (PMID 33014814, 2020). "We employed three human lung cancer cell lines, namely, H522, H1650, and H1975, which express the wild-type EGFR, 19th exon-deleted EGFR, and EGFR T790M-L858R, respectively." (PMID 33092268, 2020). "The pharmacological inhibition of EGFR in lung cancer results in apoptosis and cellular growth arrest with systemic effects, not only in tumor cells, but also in keratinocytes." (PMID 33015988, 2020). "We have developed EGFR TKI drug‐tolerant (DT) human lung cancer cell lines as a model for de novo resistance." (PMID 32123859, 2020). "When the T790M mutation of the EGFR gene is timely detected, the resistance to the TKI drug can be overcome by selecting alterative options to improve the outcomes of patients with lung cancer." (PMID 33007940, 2020). "EGFR and KRAS are the most frequently mutated genes in lung cancer, being active research topics in targeted therapy." (PMID 32107398, 2020). "Together, these results indicated the potential synergy of the BBR and gefinitib combination on the growth, migration, invasion inhibition and enhanced cell death in NSCLC including the EGFR‐TKI–resistant lung cancer cells." (PMID 32248643, 2020). "Metastatic EGFR T790M-positive NSCLC is treated with osimertinib, which is now approved for first-line treatment of EGFR-mutant lung cancer." (PMID 35582610, 2020). "Since brain imaging is essential to the diagnostic assessment of Stage IV NSCLC, a specific examination focused on the eyes should be recommended, particularly when EGFR-mutant lung cancer patients experience visual symptoms, such as visual disturbance." (PMID 33272243, 2020). "Afatinib is an anti-tumor agent of a second-generation epidermal growth factor receptor (EGFR) tyrosine kinase inhibitor, which is commonly used to treat lung cancer." (PMID 32503307, 2020). "Two previous studies investigating the role of miR-7 in lung cancer, which shares risk factors with HNC, reported that miR-7 is induced by EGFR/Ras/ERK/Myc signaling leading to aberrant cell proliferation and migration." (PMID 32872541, 2020). "Coupled with further development of lung cancer genomics, epidermal growth factor receptor (EGFR) tyrosine kinase inhibitors (TKIs) provide an effective treatment for patients with the advanced lung adenocarcinoma." (PMID 32563259, 2020). "The status of Akt activation also relates to anti-EGFR therapy resistance in head and neck squamous cell carcinoma and lung cancer." (PMID 32318334, 2020). "With this in vivo model we undertook an unbiased functional genomics screen and identified aryl hydrocarbon receptor (AHR) as suppressor of metastatic spread in EGFR-driven lung cancer." (PMID 33214553, 2020).
lung cancer (continued). "Targeted therapy revolutionized the treatment of EGFR mutant non–small cell lung cancer (NSCLC) with improved response rates over standard chemotherapy, and has become the standard first‐line treatment for patients harboring EGFR mutations." (PMID 32125091, 2020). "We demonstrated that eEF2K inhibited lung cancer cells proliferation and affected the inhibitory effects of EGFR inhibitor gefitinib." (PMID 32054489, 2020). "EGFR is one of the most frequently altered genes in lung cancer, especially in Asian adenocarcinoma subgroup (Dearden, Stevens, Wu, & Blowers, 2013)." (PMID 32757330, 2020). "In conclusion, using in vitro and in vivo EGFR-mutant lung cancer models with acquired resistance to EGFR TKIs, metformin was found to inhibit proliferation and promote apoptosis of EGFR-mutant lung cancer cells, especially acquired resistant cells." (PMID 33014814, 2020). "In summary, our findings demonstrated that FAM83A plays an oncogenic role in regulating lung cancer cell growth and motility via modulating EGFR/MAPK/CHKA signaling activity." (PMID 33266425, 2020). "The high IDAcomboscore predicted for this combination supports this possibility and suggests that this combination should be further investigated for use in the first-line therapy of EGFR wild type lung cancer." (PMID 33203866, 2020). "EGFR is a well‐characterized driver of a subset of lung cancers, with activating alterations predicting sensitivity to epidermal growth factor receptor tyrosine kinase inhibitors (EGFR‐TKIs) reported in 10%–35% of lung adenocarcinomas." (PMID 32776462, 2020). "Previous studies showed that nuclear EGFR happened in cetaximub-resistant lung cancer and in gefitinib-resistant breast cancer." (PMID 31936895, 2020). "TAR RNA-bearing exosomes can induce proinflammatory cytokines in primary macrophages and stimulate proliferation, migration, and invasion of head and neck and lung cancer cells in an epidermal growth factor receptor (EGFR)-dependent manner." (PMID 32051269, 2020). "EREG plays a carcinogenic role by binding to EGFR in various human tumors, such as colorectal cancer, nonsmall cell lung cancer, and gliomas." (PMID 33456463, 2020). "Research shows that miR-539 inhibits lung cancer cell proliferation and metastasis by directly targeting EGFR." (PMID 33148251, 2020). "The overall impact of EGFR inhibitors on intracellular calcium regulation in lung cancer cells is required to be investigated further." (PMID 33042262, 2020). "To investigate drug resistance to EGFR TKIs, we have developed lapatinib‐ and gefitinib‐tolerant lung cancer cell lines as models for de novo drug resistance." (PMID 32123859, 2020). "We investigated the function of BASP1 in metastatic lung cancer cells, focusing on the interaction between EGFR and BASP1, and searched for potential drugs to target the BASP1-EGFR axis to overcome TKI resistance in lung cancer." (PMID 33042262, 2020). "Another important factor that controls cellular proliferation in lung cancers (and not only) is the epidermal growth factor receptor (EGFR)." (PMID 33198090, 2020). "These indicated that relative to other lung cancer types, “EGFR Wild Type/Low PD-L1 expression” NSCLC experiences more diversified epigenetic silencing of tumor suppressors, which made its carcinogenic mechanisms more complicated." (PMID 32899191, 2020). "Amplification of MET in lung cancer is a well-known mechanism of resistance to epidermal growth factor receptor-targeted tyrosine kinase inhibitors (EGFR-TKIs)." (PMID 32290402, 2020). "We also showed that a cancer-associated arginine to histidine substitution in the epidermal growth factor receptor (EGFR-R776H) that is recurrent in lung cancers confers pH sensing to the mutant protein." (PMID 32983969, 2020).
lung cancer (continued). "It has been recently reported that Gal-3 promotes lung cancer stemness via the EGFR/c-Myc/Sox-2 pathway, and Oct4, a stemness-related transcription factor, favors Gal-3 expression, thus establishing a positive regulatory loop in lung CSCs." (PMID 33013832, 2020). "Future directions in research on UC will lead to identification of biomarkers for therapeutic stratification, such as microsatellite instability-high in various types of cancers and EGFR in lung cancer." (PMID 33004032, 2020). "Studies have shown that GPR171 enhanced proliferation and metastasis of lung cancer in an EGFR-independent manner." (PMID 33050301, 2020). "Recent work in EGFR‐mutant lung cancer revealed that amplification of the CCNE1 gene can be found in patients with acquired resistance to EGFR inhibitors and specifically with acquired resistance to osimertinib." (PMID 32558295, 2020). "Consistently, we found that metformin inhibited NF-κB activity and, as expected, suppressed proliferation and promoted apoptosis of EGFR-mutant lung cancer cells in a concentration-dependent manner." (PMID 33014814, 2020). "AZD1480 (a JAK1/2-TKI) impaired tumor growth in an EGFR-driven lung cancer mouse model and blocked growth of xenografted solid tumor cells." (PMID 32365499, 2020). "The development of acquired resistance to osimertinib (Osim), an FDA‐approved third‐generation epidermal growth factor receptor (EGFR) inhibitor for the treatment of EGFR‐mutant nonsmall cell lung cancer, limits the long‐term benefits for patients." (PMID 32003107, 2020). "Third, patients with high PAK1 expression and EGFR mutant lung cancer showed poor prognosis and survival." (PMID 33261184, 2020). "In contrast, miR‐646 was reported as an oncogenic miRNA in pancreatic cancer, or a critical negative regulator of the EGFR pathway in lung cancer." (PMID 32347652, 2020). "To begin testing this scenario, we first analyzed the Cancer Cell Line Encyclopedia (CCLE) database and found that TF mRNA level tends to be higher in the EGFR-mutant (EGFR-mut) lung cancer cell lines compared to that of EGFR-wild type (EGFR-wt) cell lines." (PMID 32923403, 2020). "Co-occurrence of mutation in AGTPBP1 and other altered biomarkers EGFR, KRAS, BRAF, ALK and ROS1 in lung cancer was analyzed." (PMID 33276627, 2020). "EGFR-dedicated therapies are currently used as first- and second-line lung cancer treatments, and several others are in development." (PMID 33396348, 2020). "CBLC can be recruited into the epidermal growth factor receptor (EGFR) to increase EGFR ubiquitination, and thereby downregulate EGFR signaling in lung cancer patients." (PMID 32580248, 2020). "Similar PCR and IHC results for expression frequency were obtained in an analysis of patients with EGFR-positive and EGFR-negative lung cancer." (PMID 32127616, 2020). "Targeted drugs such as epidermal growth factor receptor (EGFR)-tyrosine kinase inhibitors (EGFR-TKIs) represent one of the vital advances in lung cancer treatment." (PMID 33276757, 2020). "Dasatinib also inhibited the invasion of lung cancer cells (A549 and H1299) contained EGFR wildtype and gefitinib-resistance (H1975) contained EGFR mutation." (PMID 33344441, 2020). "While Ki-67 is a marker of proliferation that is well studied in lung cancer, EGFR has a less clear impact and its prognostic role is obscured by new therapies currently employed in clinical practice (such as EGFR-TKIs)." (PMID 33198090, 2020). "A previous study showed that targetable activating alterations in lung cancer genes, such as EGFR, ALK, RET and ROS1, are mutually exclusive molecular events." (PMID 32729257, 2020). "EGFR-targeted therapy such as EGFR tyrosine kinase inhibitors (EGFR-TKIs) alters the tumor microenvironment in lung cancer." (PMID 32206449, 2020). "MS analyses of protein phosphorylation in mouse models of human lung cancers, including those with enhanced EGFR and MET signaling, have identified phosphorylation of Tyr-1510 on IQGAP1." (PMID 33087447, 2020).